MORN2 (MORN repeat containing 2)
Description:
Might have a role in spermatogenesis.
Synonyms: MOPT; BLOCK27
Tractability: No criterion of Open Targets' tractability assessment is met for any kind of drug.
Gene: Protein-coding gene on chromosome 2 (38,875,976 to 38,882,709, forward strand). Ensembl gene ENSG00000188010.
Subcellular location: Cytoplasmic vesicle, secretory vesicle, acrosome; Nucleus
Subcellular location (Human Protein Atlas): Nucleoplasm
Gene Ontology:
Molecular function: protein binding
Cellular component: nucleus; acrosomal vesicle
Genetic constraint (gnomAD): Loss-of-function variants: 6 observed, 4.94 expected, observed/expected ratio (o/e) 1.22, 90% interval 0.64 to 1.88. That is too few expected variants to judge how well the gene tolerates losing a copy. Missense variants: 53 observed, 40.04 expected, observed/expected ratio (o/e) 1.32, 90% interval 1.06 to 1.66. Synonymous variants: 16 observed, 12.7 expected, observed/expected ratio (o/e) 1.26, 90% interval 0.85 to 1.82.
Homologues: Orthologues: pig MORN2 (89% identical), dog MORN2 (87% identical), mouse Morn2 (87% identical), tropical clawed frog morn2 (55% identical), chimpanzee MORN2 (52% identical), macaque MORN2 (50% identical), zebrafish morn2 (48% identical). Paralogues in human: RSPH1 (27% identical), MORN1 (25% identical), MORN3 (23% identical), RSPH10B (21% identical), RSPH10B2 (21% identical), SETD7 (21% identical), ALS2CL (20% identical).
Diseases named in the same sentence as MORN2 in open-access papers:
MORN2 is named in the same sentence as 6 diseases in open-access papers, as found by Europe PMC text mining. Sharing a sentence is not in itself a finding about the gene and the disease. The quoted sentences say what the papers report.
fungal infections (1 paper, 2021). "The elimination of C. albicans by planarians is associated with the induction of Smed-MORN2, Smed-TAK1 and Smed-p38 genes, demonstrating the importance of MORN2 in planarian immunity against fungal infections as well." (PMID 33732660, 2021).
male infertility (1 paper, 2024). The inability of the male to effect fertilization of an ovum after a specified period of unprotected intercourse. "Collectively, our findings demonstrate that sperm from Morn2–/– mice can penetrate the ZP and fuse with oocytes in vitro but are unable to complete fertilization in vivo, likely due to their poor motility thus resulting in male infertility." (PMID 38443933, 2024). "We hypothesize that this is related to the poor motility of Morn2–/– sperm, which are unable to transit through female reproductive tract and reach the ampulla in order to combine with the egg, thus resulting in male infertility." (PMID 38443933, 2024).
bacterial infection (1 paper, 2024). "A previous study predicted that MORN2 functions in the dynamic regulation of acrosome biogenesis during late spermiogenesis, and MORN2 has been shown to function in LC3-associated phagocytosis and in resistance to bacterial infection in planarians." (PMID 38443933, 2024).
cancer (1 paper, 2016). A tumor composed of atypical neoplastic, often pleomorphic cells that invade other tissues. "These variants were found in genes associated with cancers (ANKRD35, DNAH9, MAGEC1, TOX3) or participating in cancer-related signaling pathways (THSD1, MORN2, PTCRA)." (PMID 26822197, 2016).
MORN2 also shares sentences with these, for which no sentence is quoted: infection (2 papers); Infertility (1).